CTSD (cathepsin D)
Diseases named in the same sentence as CTSD in open-access papers (continued):
Sharing a sentence is not in itself a finding about the gene and the disease.
Parkinson disease (continued). "Cathepsin D serves as the principal endopeptidase involved in the degradation of long-lived proteins, including α-synuclein—a process relevant to neurodegenerative diseases such as Parkinson’s disease (PD) and dementia with Lewy bodies (DLB)." (PMID 40869205, 2025). "It is worth noting that, Cathepsin D is responsible for degrading misfolded proteins and regulating the activities of various polypeptides, enzymes, and growth factors in conditions such as Parkinson’s disease and Alzheimer’s disease." (PMID 39420987, 2024). "Specifically, Cathepsin B and Cathepsin D were found to be protective against Parkinson’s disease." (PMID 39420987, 2024). "A possible explanation for cathepsin D low levels in patients with Parkinson’s disease might be the down-regulation of the M6P receptor due to its compromised retrograde transport from endosomes to the trans-Golgi network." (PMID 34198733, 2021). "Therefore, it is essential to investigate the strong correlation between Cathepsin D and Parkinson’s disease, as it could potentially serve as a promising target for the treatment and prevention of this neurodegenerative disorder." (PMID 39420987, 2024). "One recent study has found that lysosomal protease Cathepsin D, Lysosome Associated Membrane Protein 1 (LAMP1), and Heat Shock Protein 73 (HSP73) immunoreactivities are significantly decreased (each protein to about 50%) in Parkinson's disease substantia nigra neurons." (PMID 20388210, 2010). "Fucoidan from brown algae inhibited the expression of cathepsin D and Bax in the murine dopaminergic nerve precursor cell line, MN9D (neuroblastoma), and indicated its prospective role as a neuroprotective agent in Parkinson’s disease treatment." (PMID 34198733, 2021). "This suggests that ambroxol is inducing a general increase in lysosomal mass, with improvement of glucosylceramidase activity in Gaucher disease, Parkinson’s disease with GBA mutations and non-manifesting carriers resulting in a fall in cathepsin D and beta-hexosaminidase activity." (PMID 24574503, 2014).
glioma (21 papers, 2012 to 2026). A benign or malignant brain and spinal cord tumor that arises from glial cells (astrocytes, oligodendrocytes, ependymal cells). "The CTSD gene is responsible for encoding cathepsin D, which is widely considered to be closely correlated with the prognosis of glioma." (PMID 37398678, 2023). "In agreement with the previous data demonstrating that in glioma cells, RT-associated cell death was mainly a mixture of necrosis and autophagy, we show a dose-dependent increase in cathepsin D cleavage and calpain 1 autolysis (necrosis)." (PMID 29486795, 2018). "In addition to cathepsin L being associated with the radiosensitivity of gliomas, another study also found that cathepsin D was expressed at significantly higher levels in radioresistant clones than in parental cells." (PMID 37398678, 2023). "Cathepsin D (CTSD) was also increased in EVs from more invasive cells, its release and activity is linked to glioma invasion, and may act directly by degrading local ECM structures or indirectly through activation of cysteine proteinases." (PMID 27770278, 2017). "Inhibition of cathepsin D can also improve the sensitivity of glioma radiotherapy by promoting autophagy." (PMID 37398678, 2023). "Our data demonstrate that after 48 hours of lucanthone treatment, P62 and Cathepsin D increase in both glioma cell lines, though we note a higher relative increase of both proteins in KR158 cells." (PMID 35494072, 2022). "The importance of CTSD in malignant glioma invasion was demonstrated using mass spectrometry analysis and under- or over-expression of CTSD modulated the malignant potential and radio-sensitivity of glioma cells." (PMID 34062746, 2021). "Elevated expression of cathepsin B and cathepsin D has been observed in many tumor types such as infantile hemangioma, oral tongue squamous cell carcinoma, MG, and gliomas including GB." (PMID 30949483, 2019). "These fragments have been reported as potential biomarkers of gliomas and acute renal allograft rejection and are possibly produced by cathepsin D protease activity." (PMID 31191748, 2019). "tBID activates BAX, an effector of apoptosis, and the cancer chemotherapy drug gemcitabine promotes BAX-dependent apoptosis of a glioma cell line via lysosomal ceramide accumulation and cathepsin D activation." (PMID 31474371, 2019). "In the scratch assay, when we inhibited cathepsin D activity by a chemical inhibitor pepstatin A, an inhibitor of aspartyl proteases to which cathepsin D belongs, both C6 and U251 glioma cell migration was inhibited." (PMID 23029308, 2012). "Functionally, we demonstrated that RNAi-Rab27A inhibited exocytosis of the lysosome enzyme cathepsin D and inhibition of cathepsin D enzyme activity inhibited glioma cell migration." (PMID 23029308, 2012). "RNAi-Rab27A inhibited lysosome cathepsin D exocytosis and glioma cell invasion in an in vitro assay." (PMID 23029308, 2012). "When cathepsin D was inhibited by a chemical inhibitor, glioma cell migration was inhibited in the scratch assay." (PMID 23029308, 2012). "Their findings suggest that glioma cells are sensitized to apoptosis by inhibiting autophagy, whereas cathepsin D enhances autophagy, which may indicate that cathepsin D can mediate immune escape by activating autophagy." (PMID 37398678, 2023). "Moreover, in vitro studies have shown that the manipulated inhibition or promotion of CTSD expression modulates apoptosis, proliferation, invasiveness, migration ability, and autophagy level to affect the radio-sensitivity of glioma cells." (PMID 34062746, 2021). "CTSD has been identified as an important protein related to glioma invasion." (PMID 32922940, 2020). "Besides, CTSD also played a pivotal modulatory role in invasion process of hepatocellular carcinoma and glioma." (PMID 30430081, 2018).
glioma (continued). "Cathepsin D has also been observed in numerous cancers, including gliomas, with significantly elevated levels of expression in more aggressive gliomas, such as GBM, implying that serum cathepsin D levels could be a prognostic marker for GBM." (PMID 28611989, 2017). "Interestingly, elevated CTSD serum levels correlate with glioma grade and high CTSD transcript levels in GBM tumours is associated with reduced survival." (PMID 27770278, 2017). "In the present study, we found that Rab27a colocolized with cathepsin D in glioma cell lysosomes." (PMID 23029308, 2012). "For example, Cathepsin D is a potential serum marker for poor prognosis in glioma patients." (PMID 23029308, 2012). "We also found large amounts of cathepsin D within glioma cell lysosomes in the permeabilized cells." (PMID 23029308, 2012). "We found that rab27A was expressed in glioma cells, and colocalized with cathepsin D in lysosome." (PMID 23029308, 2012). "In addition, the knockdown of VEGF receptor 2, AKT3, and PI3KCA in glioma cells by antisense RNA can significantly reduce the expression of cathepsin D, suggesting that the relationship between lysosomal peptidases and VEGF may not be unidirectional." (PMID 37398678, 2023). "Since cathepsin D is a normal and major component of lysosomes, frequently used as a marker, these results confirm that the mechanism by which RNAi-Rab27a inhibits glioma invasion is by inhibiting lysosomal exocytosis of cathepsin D or the extracellular release of other lysosomal enzymes." (PMID 23029308, 2012). "Furthermore, Rab27A and cathepsin D colocaolized in glioma cell lysosomes." (PMID 23029308, 2012). "Our cophenetic correlation coefficient calculations (CCC) are in support of EMMPRIN/CD147, CD99, Cathepsin D, Intβ1, ADAM9/-17, and Galectin-3 being suitable biomarkers for glioma cells and potentially, SLGCs." (PMID 38306361, 2024). "However, as PAI-1 is also abundant outside of Cathepsin D + areas, we attempted to localize intracellular PAI-1 in the glioma model after lucanthone stimulation." (PMID 40684232, 2025). "However, in recent years, many molecular and genetic biomarkers have been identified as noninvasive factors in the diagnosis of gliomas, including glutamate, ATIA, cathepsin D, GADD45, YKL40, Ki67, MIP-1, and CDKN2A." (PMID 35053475, 2022). "Likewise, cathepsin D (CTSD) remains a normal and major component of lysosomes in glioma cells compared to normal astrocytes." (PMID 36552871, 2022). "While the role of cathepsin D in GBM remains unclear, it has similar proteolytic actions on the extracellular matrix as cathepsin B, and a positive correlation between the expression level of cathepsin D and glioma grade has been observed." (PMID 28611989, 2017).
neuroblastoma (19 papers, 2011 to 2025). Neuroblastoma (NB) is the most common solid, extracranial childhood tumor. "Accordingly, two-thirds of patients at INSS Stage 4 present with a low level of CTSD expression, indicating that neuroblastomas with CD deficiency grow and progress faster than neuroblastomas that express a high level of CD." (PMID 35563171, 2022). "Overexpression of cathepsin D is protective against α-synuclein-mediated neurotoxicity in SH-SY5Y neuroblastoma cells, while Y125A mutation at the α-synuclein cleavage site of cathepsin D leads to neuroprotection resistance." (PMID 34827514, 2021). "In order to examine CTSD variants in neural-like cells, a CTSD knockout (KO) was established in human neuroblastoma (SH-SY5Y) and neuroglioma (H4) cell lines by CRISPR/Cas9 technology." (PMID 33681191, 2021). "Cathepsin D has been associated with chemoresistance in N-MYC-overexpressing neuroblastomas." (PMID 35563171, 2022). "In a 2008 study focusing on the role of cathepsin D (CTSD), this was shown to also confer protection to neuroblastoma cells against doxorubicin-induced apoptosis." (PMID 40426729, 2025). "This suggests that CTSD expression can be modified to confer a survival advantage during the growth and spread of neuroblastoma cells." (PMID 40426729, 2025). "A total of 75% of patients with stage 4 neuroblastoma had low expression of CTSD in their tumour tissue." (PMID 40426729, 2025). "We demonstrated that cathepsin D (CD) counteracts EGF-induced neuroblastoma cell growth in 2D by downregulating EGFR/MAPK signaling." (PMID 38611021, 2024). "Recently, we demonstrated that lysosomal cathepsin D (CD), a ubiquitous soluble aspartic endopeptidase, contrasts neuroblastoma cell proliferation." (PMID 38611021, 2024). "To obtain an insight into the functional role of CTSD in pediatric neuroblastoma patients, we performed an in silico transcriptomic analysis of the genes correlated to it." (PMID 35563171, 2022). "This work aimed to understand the mechanisms linking EGFR stimulation and cathepsin D expression with neuroblastoma progression and prognosis." (PMID 35563171, 2022). "Cathepsin D overexpression decreased the proliferative potential of neuroblastoma cells through downregulation of the pro-oncogenic MAPK signaling pathway." (PMID 35563171, 2022). "To investigate the role of cathepsin D in determining neuroblastoma growth we sought to genetically manipulate its expression." (PMID 35563171, 2022). "In the present study, we interrogated datasets from the TCGA database to determine the clinical relevance of CTSD status in pediatric neuroblastoma patients highly expressing EGFR." (PMID 35563171, 2022). "Another study performed on the human neuroblastoma SH-SY5Y cell line demonstrated the cathepsin D involvement in the mitophagy process." (PMID 34198733, 2021). "It demonstrated that necrostatin-1 induced cathepsin D inhibition in a cell line of differentiated human neuroblastoma RA-SH-SY5Y." (PMID 34198733, 2021). "The active role of cathepsin D in oxidative stress–induced cell death in neuroblastoma cells was shown by siRNA-mediated downregulation of the enzyme, besides using PsA." (PMID 31960265, 2020). "For example, PPT1/CLN1 was shown to interact with CTSD/CLN10 in SH-SY5Y human neuroblastoma cells, possibly due to their common function as lysosomal enzymes." (PMID 32430003, 2020). "It should be mentioned that once translocated into the cytosol upon oxidative stress–induced permeabilization of the lysosomes (H2O2 for 30 min), cathepsin D was shown to act on Bax to induce apoptosis in human neuroblastoma cells." (PMID 31960265, 2020). "Autophagic activity was monitored by the changes in GFP-LC3 localization and protein levels of Beclin1, LC3-II, cathepsin D and p62 in neuroblastoma SH-SY5Y cells underwent serum deprivation." (PMID 23658815, 2013). "In vitro overexpression of Cathepsin D in a human neuroblastoma cell line led to a significant increase in the number of the lysosomes." (PMID 21777416, 2011).
neuroblastoma (continued). "To address a possible common role of highly expressed and functional important CTS proteases, we generated CTSB-, CTSD-, CTSL-, and CTSBDL-triple deficient (KO) human neuroblastoma-derived SH-SY5Y cells and CTSB-, CTSD-, CTSL-, CTSZ and CTSBDLZ-quadruple deficient (KO) HeLa cells." (PMID 38775843, 2024). "Our data suggest that chemotherapeutics that inhibit the EGFR pathway, along with stimulators of cathepsin D synthesis and activity, could benefit neuroblastoma prognosis." (PMID 35563171, 2022). "We tested this hypothesis in engineered neuroblastoma cells in which cathepsin D was overexpressed or knocked down." (PMID 35563171, 2022). "Gene correlation analysis in pediatric neuroblastoma patients revealed that individuals bearing a high EGFR transcript level have a good prognosis only when CTSD (the gene coding for the lysosomal protease Cathepsin D, CD) is highly expressed." (PMID 35563171, 2022). "Whether cathepsin D plays an active role in EGFR-linked growth and progression of neuroblastoma remains to be elucidated." (PMID 35563171, 2022). "Taken together, these data demonstrate that the level of CD expression impacts on the proliferative ability of neuroblastoma cells, and validate the bioinformatic data showing a strong inverse correlation between the expression of CTSD and genes involved in cell cycle progression." (PMID 35563171, 2022). "These preliminary data provided the rationale to speculate that cathepsin D could be involved in EGFR regulation of neuroblastoma growth." (PMID 35563171, 2022). "The present work demonstrates, for the first time, a novel antiproliferative role of cathepsin D that may be exploited to improve neuroblastoma management and treatment." (PMID 35563171, 2022). "In SH-SY5Y-APPswe neuroblastoma, TFEB induced an upregulation of several lysosomal and autophagic mRNAs, but interestingly, it had strong effects on the expression of cathepsin mRNAs and particularly on that of CTSD encoding cathepsin D, one of the main proteases involved in C99 degradation." (PMID 32408680, 2020). "Further, in silico transcriptome analysis revealed that neuroblastoma patients with high EGFR and high CTSD levels had a better prognosis compared to patients bearing high EGFR and low CTSD." (PMID 35563171, 2022). "First, we focused on the prognostic value of CTSD in pediatric neuroblastoma patients, and we found that the 75% of patients at INSS Stage 4 showing low CTSD expression had the worst prognosis." (PMID 35563171, 2022). "Three further studies looked at cathepsin expression in SH-SY5Y neuroblastoma cell lines, with one suggesting that higher levels of CTSD expression increased median survival in a non-statistically significant manner." (PMID 40426729, 2025). "In our previous work, we found that prognosis was improved in patients bearing a neuroblastoma with high expression of CTSD regardless of the expression of EGFR." (PMID 38611021, 2024). "Additionally, the heatmap depicting the mRNA expression (bottom part) indicates that most neuroblastoma patients display high levels of MYCN, while the mRNA levels of EGFR, EGF, MAPK1 and CTSD are low or very low." (PMID 38611021, 2024). "Our findings encourage in vitro testing of the effects of resveratrol as adjuvant therapy for neuroblastomas low-expressing cathepsin D and not responding to the EGFR inhibitor gefitinib." (PMID 35563171, 2022). "Finally, in SH-SY5Y human neuroblastoma cells, knockdown of ATP13A2/CLN12 reduces the amount and activity of CTSD/CLN10." (PMID 32430003, 2020). "Here, we looked for the correlation between the MYCN, CTSD, EGFR and MAPK1 genes and checked the prognostic value of CTSD in the context of MYCN positive and negative neuroblastomas." (PMID 38611021, 2024).
neuroblastoma (continued). "It has also been reported that the accumulation of LAPTM5 protein in Ad-LAPTM5-infected neuroblastoma cells induces caspase-independent non-apoptotic cell death with lysosomal destabilization and LMP, which allows lysosomal cathepsin D release into the cytosol." (PMID 28464033, 2017).
lysosomal storage disease (18 papers, 2007 to 2025). A metabolic disorder caused by mutations in proteins critical for lysosomal function, including lysosomal enzymes, lysosomal integral membrane proteins, and proteins involved in the post-translational modification and trafficking of lysosomal proteins. "Mutations within the CTSD gene have been linked to the severe neuropathic lysosomal storage disorder NCL10." (PMID 33681191, 2021). "Axonal swellings containing autophagosome-like structures are observed in mouse models of lysosomal storage diseases such as neuronopathic GD mice, Niemann-pick type C1 mice, Cathepsin D-deficient mice, and Cathepsin B/L double-deficient mice." (PMID 25835295, 2015). "Spleen cells from cathepsin D deficient chimaeric mice contained an increased number of autofluorescent granules characteristic of lipofuscin positive lysosomal storage diseases." (PMID 17897442, 2007). "Cathepsin D deficient mice exhibit various neurological abnormalities, and these have been related to neuronal degeneration associated with the development of lipofuscin containing granules, characteristic of a class of lysosomal storage diseases." (PMID 17897442, 2007). "Defective lysosomal function (lysosomal storage diseases) and endocytic function (neurodegenerative diseases) are frequently associated with extracellular deposit formation (eg. amyloid plaques) and mice that express a mutant form of cathepsin D develop BlamDs." (PMID 23460904, 2013). "Inactivation of cathepsin D in flies results in age-dependent neurodegeneration and recapitulates the key features of neuronal ceroid lipofuscinoses, a family of lysosomal storage disorders." (PMID 25173815, 2014). "Since Cathepsin D deficiency is associated with human lysosomal storage disorders, our studies suggest that lysosomal ATP/SLC17A9 could be involved in lysosomal storage disorders." (PMID 35269509, 2022). "CTSD knockout mice develop a lysosomal storage disease that ultimately leads to death." (PMID 35351824, 2022). "Finally, in addition to GRN, we found upregulation of other lysosomal genes frequently dysregulated in lysosomal storage disorders such as NEU1, NPC2, PSAP, CTSD, LAMP1, and HEXA." (PMID 38643236, 2024).